BRCA2 (BRCA2 DNA repair associated)
Diseases named in the same sentence as BRCA2 in open-access papers (continued):
Sharing a sentence is not in itself a finding about the gene and the disease.
tumor (continued). "Nonetheless, ambiguity persists regarding the extent to which the functional assessment of HR activity can serve as a predictor for the susceptibility of tumor cells harboring BRCA1 or BRCA2 variants to the effects of PARP inhibitors and DNA-damaging agents." (PMID 38397209, 2024). "In this report, we present a case of a patient with metastatic uLMS, positive for a somatic BRCA2 mutation who showed significant reduction in tumor size after initiation of PARPi therapy." (PMID 39666931, 2024). "This unusual tumour spectrum and the staggered occurrence of these tumours required multiple rounds of genetic testing and led to a delayed diagnosis of the BRCA2-associated tumour predisposition." (PMID 39702187, 2024). "The SBS26-positive patients displayed a BRCA1/2 wildtype for the germline and tumor (n = 2), a germline wild type (n = 1), or had a germline BRCA2 mutation (n = 1) and were treated with niraparib (n = 3) or olaparib (n = 1)." (PMID 38927686, 2024). "In samples of our patient’s buccal swab, peripheral blood, and tumor tissue, a pathogenic variant in the partner and localizer of BRCA2 (PALB2) gene was found." (PMID 38817905, 2024). "Patient characteristics were generally similar between age subgroups for disease stage at baseline, best response to first-line PBC, postoperative residual disease, and tumor BRCA2 mutation status." (PMID 38833992, 2024). "Loss of the wild-type BRCA2 allele in the tumor results in an excellent early, complete metabolic response due to a somatic aberration that likely leads to deregulation of the cellular HR function responsible for increased sensitivity to trabectedin." (PMID 38674402, 2024). "As a result, BRCA2-deficient tumor cells need to partially restore these functions or possess alternative repair pathways to survive, owing to highly unstable genomes and chromosomes." (PMID 37934606, 2024). "Mutations affecting other components of the HR machinery, such as BRCA1 or BRCA2, increase the rate of genetic mutations, leading to substantially increased tumor risk." (PMID 38530355, 2024). "This specificity is crucial as itallowsprecise inhibition of PARP-1 in tumor cells with Breast Cancer 1 protein(BRCA1) or BRCA2 deficiencies." (PMID 39346823, 2024). "For example, truncating mutations are the most frequent mutations seen in BRCA2, a tumor-suppressor gene that localizes to the nucleus and takes part in repair of DNA double-strand breaks." (PMID 38713862, 2024). "In Group 2, four out of 174 participants with neoplasms carried variants in BRCA2 (rs768580992, review status “reviewed by expert panel”) and MUTYH (rs36053993, rs36053993, and rs34612342; review status “multiple submitters”)." (PMID 39301547, 2024). "BRCA2: Breast cancer type 2 susceptibility protein (BRCA2) is a tumor suppressor and recombination mediator which loads RAD51 on RPA-coated ssDNA." (PMID 39359934, 2024). "Patient EOC105 was known to have a somatic BRCA2 mutation in the primary tumor sample and initially responded well to platinum-based chemotherapy." (PMID 37924564, 2024). "Tumor analysis revealed both allelic loss at the BRCA2 locus and deficiency in mismatch repair gene protein expression (dMMR), indirectly implicating both genes as contributors to the tumorous phenotype in that case." (PMID 39102164, 2024). "In conclusion, these results show that PP2A is a synthetic lethal target for BRCA2-deficient tumor cells, and the PP2Ais reduce potential drug resistance to PARPis and enhance their therapeutic effect." (PMID 37934606, 2024). "Another essential gene for repairing DNA, the partner and localizer of BRCA2 (PALB2) is a tumor suppressor gene, also identified as a susceptibility gene for human BC." (PMID 38338903, 2024).
tumor (continued). "Circulating tumour DNA analysis from the phase 2 TRITON2 trial demonstrated the prevalence of reversion mutations in BRCA1 or BRCA2 after progression on rucaparib." (PMID 37345149, 2023). "Mutational signature analysis of these five pediatric tumors revealed that only the tumor with pathogenic homozygous BRCA2 mutation, that is, biallelic inactivation, showed SBS3 and ID6 signature activity." (PMID 36702933, 2023). "The results of low HRDetect scores in our high-risk non-BRCA1/BRCA2 familial breast tumours are also supported by an independent method, our RNA-classifier, although a few tumours with low HRDetect scores were BRCA1- or BRCA2-like with this profile." (PMID 37316882, 2023). "Among INFORM tumors, only the single tumor with a BRCA2 pathogenic homozygous mutation (INF_R_1076) has been identified as BRCA2 HRD phenotype with high probability (0.82)." (PMID 36702933, 2023). "Cell viability analyses showed that NCT-505 and olaparib can synergistically reduce tumor cell viability in OV35 and OV39 HGSOC tumor organoids, which possess BRCA2 and BRCA1 mutation, respectively, as well as positive ALDH1A1 expression." (PMID 37429899, 2023). "The separation from the non-BRCA1/BRCA2 tumours is mainly driven by homologue repair deficiency (HRD), i.e. the HRD-associated substitution signature (SBS) 3, where a higher level is detected in the BRCA1/BRCA2-mutated tumours." (PMID 37316882, 2023). "One patient had a bilateral multicentric tumor (patient 6) in the context of a BRCA2 pathogenic germline mutation." (PMID 36879128, 2023). "The genetic landscape, especially mutations in BRCA1 and BRCA2, plays a pivotal role in BC development by disrupting the normal tumor-suppressive functions, thereby propelling unchecked cellular proliferation and genomic instability." (PMID 38066539, 2023). "Functional mutations in BRCA1 and BRCA2 have been identified in tumor cells, impairing their HRR capacity." (PMID 37958290, 2023). "Based on the aggressiveness of HRD-mutated neoplasms, an earlier and more aggressive therapeutic approach should be followed for BRCA2-mutated tumors." (PMID 37511177, 2023). "To examine the impact of BRCA2 R2971Q variant on tumor predisposition, we generated a cohort of Brca2RQ/+, Brca2RQ/RQ and Brca2RQ/KO animals and monitored their tumor-free survival for 750 days." (PMID 37980415, 2023). "In preclinical models, a response to HER2, TKIs were seen in tumours with inactivated BRCA2 mutations." (PMID 36831687, 2023). "Specifically, mice with a homozygous germline deletion of Brca2 gene exon 27 exhibit a decrease in perinatal viability, decreased survival, and also pronounced tumor susceptibility." (PMID 36702902, 2023). "In LGG, mutations in BRCA1 and BRCA2 have been associated with a higher risk of tumor recurrence and a poorer prognosis." (PMID 37660060, 2023). "Post-treatment analysis of tumor biopsies revealed that most patients with platinum-resistant recurrent OC harboring secondary mutations restoring BRCA2 activity exhibited progressive disease following olaparib therapy." (PMID 37048111, 2023). "Homologous recombination deficiency due to mutational inactivation of the BRCA1 and BRCA2 tumor suppressor genes is known to make human tumors susceptible to PARP inhibitors and platinum-based chemotherapies." (PMID 37906280, 2023). "In the initial in vitro analyses, the Brca-deficient ID8 models were differently sensitized to olaparib-induced toxicity, with the Brca2-deficient tumours demonstrating greater susceptibility to PARP inhibition." (PMID 38017453, 2023). "Over the 14-day treatment period, JQ1 treatment significantly reduced the tumor volume in both control and Brca2-deficient tumors, but more significant reduction in Brca2-deficient tumors." (PMID 37735513, 2023).
tumor (continued). "The analysis evidenced tumor-specific BRCA2 secondary mutations in olaparib-resistant metastasis, restoring full-length BRCA2 functional protein." (PMID 37569269, 2023). "For example, the efficacy of PARP inhibitors in tumours with germline BRCA1 or BRCA2 mutations has been well established, in both metastatic and early disease settings in breast and ovarian cancer." (PMID 37491606, 2023). "Another patient with high SBS3 and a low HRD score had a benign germline BRCA2 mutation, which was homozygous in the tumor due to loss of heterozygosity." (PMID 36964191, 2023). "Olaparib and combination therapies similarly improved the median survival of Brca1- and Brca2-deficient tumour-bearing mice." (PMID 38017453, 2023). "Specifically, higher mB7-H3 was present in tumours with bi-allelic BRCA2 mutation mutations (n=13, p=0.003) or ATM protein loss (n=16, p=0.02) than in those without DDR." (PMID 36114082, 2023). "Hereditary PC with pathogenic BRCA2 variants exhibits bi‐allelic BRCA2 inactivation by germline mutation and somatic loss of heterozygosity (LOH), while PC with somatic BRCA2 alterations exhibits two‐hit alterations in the tumor." (PMID 36645189, 2023). "Exon 27 of the tumor suppressor BRCA2 encodes a portion of the protein crucial for DNA repair, genome maintenance, and tumor suppression." (PMID 36702902, 2023). "Our IHC clinical data provide evidence that MRE11 overexpression in BRCA2-deficient somatic tumours can influence aggressive clinicopathological phenotypes." (PMID 37446144, 2023). "The aggressiveness of BRCA2-mutated neoplasms has been attributed to the fact that these tumors develop a subpopulation of cells that are castrate-resistant and can grow independently, even after the administration of antiandrogen therapy." (PMID 37511177, 2023). "Three non-BRCA1/BRCA2 tumours also had a HRDetect score of > 0.99 and were classified as having BRCA1/BRCA2-deficient tumours." (PMID 37316882, 2023). "Altogether, this indicates that POLQ inhibition induced DNA damage to ultimately trigger an influx of CD8+ T cells to suppress tumor growth in BRCA2-deficient PDAC, and STING represents a critical component of this pathway." (PMID 36976649, 2023). "FoundationOne testing on the lesions revealed BRCA2 loss in the tumor, and germline DNA testing was performed in light of this." (PMID 38161892, 2023). "BRCA2 mutations are identified in up to 14% of ACs and, differently from other tumor types, therapeutic implications remain to be defined." (PMID 36998040, 2023). "Fifteen percent of EOC tumors carry mutations or deletions of BRCA1 or BRCA2, a defect in homologous recombination (HR) that renders these tumor cells vulnerable to synthetic lethality induced by inhibitors of poly (ADP-ribose) polymerase (PARP)." (PMID 37568736, 2023). "CX-5461 was also recently shown to decrease cell viability in ATRX-deficient glioma and BRCA1/BRCA2-deficient tumor cells." (PMID 36770824, 2023). "The only germline BRCA2 pathogenic variant reported in a patient diagnosed aged ≥80 was detected in germline and tumour DNA (BRCA2 c.4478_4481del; GIS 83)." (PMID 36765687, 2023). "We analysed tumours that contain either germline or somatic BRCA2 mutations, on one or both alleles, to provide a sufficient sample size." (PMID 37626143, 2023). "Clustering based on these signatures supported that BRCA1/BRCA2-mutated tumours are clearly separated from non-BRCA1/BRCA2 tumours." (PMID 37316882, 2023). "NGS CGP on cftDNA identified BRCA2 pathogenic variants in one case where tumor-based testing failed." (PMID 37932736, 2023). "BRCA2-deficient tumours that are unable to repair DSBs accumulate lethal DSBs, which leads to selective cell death." (PMID 37446144, 2023). "Meanwhile, the patient underwent a BRCA test, which documented a germline mutation of BRCA2; microsatellite status was also analyzed, confirming a microsatellite stable tumor (MSS)." (PMID 35200549, 2022).
tumor (continued). "Germline BRCA2 PSV are associated with higher tumor stage, Gleason grade, and prostate-specific antigen (PSA) levels at diagnosis." (PMID 35715489, 2022). "BRCA1 mutations are more often associated with triple negative breast cancer (TNBC), whereas BRCA2 mutations are associated with HR-positive tumours." (PMID 35194731, 2022). "Our results demonstrate that pyridostatin effectively inhibits growth of BRCA2‐deficient xenograft tumours, thus recapitulating our in vitro results." (PMID 35107878, 2022). "The medication was approved by her insurance with the somatic BRCA2 mutation data and documented recommendation from the institutional molecular tumor board." (PMID 36330376, 2022). "The clinical implications of somatic BRCA2 mutations are poorly understood; however, all BRCA2 mutations (germline and somatic) are understood to destabilize HR, increase tumor aggression, and contribute to poor patient outcomes." (PMID 36922933, 2022). "BRCA2 is a large, complex protein that paradoxically is required for cellular viability, and yet, its loss in somatic human cells drives tumor initiation and/or progression." (PMID 36098506, 2022). "Our assumption that canonical HDR functions (RAD51 loading/filament stabilization) underlie BRCA2’s role in tumor suppression seems likely but requires definitive proof." (PMID 36098506, 2022). "Responsiveness of BRCA2−/− cells was also proven in a model of CAPAN1 (pancreatic ductal adenocarcinoma tumor) cells derived from the tumor with naturally occurring BRCA2 mutation." (PMID 36613762, 2022). "The BRCA1 and BRCA2 tumour suppressor genes encode nuclear protein products that maintain genome integrity through various roles, including DNA repair, cell-cycle regulation and apoptosis." (PMID 35668475, 2022). "Conversely, this patient had a concurrent BRCA2 mutation and tumor analysis showed loss of heterozygosity for BRCA2 only." (PMID 35159349, 2022). "While we did observe only a slight, non-significant increase in Cxcl9 ascites concentration upon Brca2 loss, Cxcl10 was more than fivefold higher than in Brca2WT tumours." (PMID 35314795, 2022). "CRISPR-Select showed large effect sizes with variants in the recessive tumor suppressors BRCA2 and PTEN20 in diploid MCF10A cells." (PMID 36471068, 2022). "Germline mutations in BRCA1 or BRCA2 tumor suppressor genes, which play important roles in homologous recombination, are found in approximately 10% of cases of epithelial OC." (PMID 36509287, 2022). "BRCA1-associated tumours are however biologically different from BRCA2-associated breast tumours, and should therefore be studied separately." (PMID 34929424, 2022). "A second participant with metastatic pancreas cancer and known pathogenic BRCA2 germline mutation (c.5946delT;p.S1982fs; rs80359550) had the best response of SD with evidence of clinical benefit (reduction in tumor markers and improvement in symptoms)." (PMID 35750695, 2022). "In contrast, these effects were abrogated in Brca2-deficient tumours, most likely due to an already high intrinsic chemokine expression." (PMID 35314795, 2022). "This study identifies tumor genetic backgrounds where to expand the use of PARPis beyond mutations in BRCA1 or BRCA2." (PMID 36969741, 2022). "Tumor-prone cells carrying BRCA2 inactivation underwent loss of chromosomal integrity and accumulated cell membrane DNA in the form of micronuclei." (PMID 36618371, 2022). "The proportion of patients carrying BRCA2 mutation was higher in the high pTyr705-Stat3 tumor group (p = 0.039)." (PMID 36017196, 2022). "This is the case for the synthetic lethality approach using PARPis in tumours with mutations in the BRCA1 or BRCA2 genes." (PMID 36139634, 2022). "BRCA1 and BRCA2 genes encode proteins that help maintain genomic stability and act as tumour suppressors." (PMID 35444210, 2022). "Pyridostatin showed selective toxicity against BRCA2‐deficient HCT116 cell‐derived tumours, similarly to its effect in DLD1 cell‐derived xenografts." (PMID 35107878, 2022).
tumor (continued). "For instance, in a phase II clinical trial, secondary resistance mutations were detected in circulating free tumor DNA in two patients with a germline BRCA2 mutation." (PMID 35785170, 2022). "Among DNA repair genes BRCA1and BRCA2 showed the greatest mutation frequency and the tumor burden increased in correlation with the number of affected DNA repair genes." (PMID 35785170, 2022). "In BRCA2‐deleted tumours, PARPi resistance can be triggered by loss of the poly(ADP‐ribose) glycohydrolase PARG." (PMID 35107878, 2022). "Given the tumor percentage of 70% and a variant allele frequency of 28.4%, it is presumed that the patient's BRCA2 PV is a monoallelic BRCA2 mutation." (PMID 36577523, 2022). "In this review, we discuss the biological functions of BRCA2 and the role of BRCA2 mutations in tumor progression and therapy." (PMID 36397405, 2022). "The association between AKT groups and tumor BRCAness was partially supported by the results on the BRCA1/BRCA2 genetic testing, which was available for 36 patients." (PMID 35053468, 2022). "Tumor cells that are defective in HR due to loss of BRCA1 or BRCA2 use alternative error-prone pathways that lead to fragmentation of the genome and ultimately result in cell death." (PMID 35203410, 2022). "Patients with BRCA2 mutations are at increased risk for PDAC onset; it has been reported that loss of BRCA2 function predisposes the pancreas to profound DNA damage that determines a major frequency of invasive neoplasia." (PMID 35205366, 2022). "This also suggests that BRCA1 and BRCA2 mutation carriers should ideally be analyzed separately, due to their tumor’s biological differences." (PMID 35507134, 2022). "Out of 641 patients analyzed, 56 (8.7%, 20 in BRCA1 and 36 in BRCA2) bore tumour BRCA PVs and 64 variants of uncertain significance (VUS)." (PMID 35463374, 2022). "Fails in detection in tumor samples (samples DNA_1-3; FFPE_1-3) corresponded to two frameshift mutations in BRCA2 (variants 2 and 6) and a splicing alteration in BRCA1 (variant 4)." (PMID 36579549, 2022). "All patients with germline mutations in PALB2(gPALB2; encoding partner and localizer of BRCA2) had treatment-associated tumor regression." (PMID 36253484, 2022). "Inactivation of Rad52 in BRCA2-deficient cells results in synthetic lethality, which makes Rad52 a tumour-specific target for therapy in BRCA2-deficient tumours." (PMID 36010882, 2022). "Tumor genomic profiling using FoundationOne CDx identified pathogenic alterations in three DNA repair genes, including BRCA2 frameshift mutation." (PMID 36092022, 2022). "Functionally, BRCA2 mutation affected the homologous recombination repair mechanism, ultimately resulting in genomic instability in tumor cells." (PMID 36147475, 2022). "The positive association between lymph node involvement and tumor size appears to be stronger in BRCA2 mutation carriers than in BRCA1 mutation carriers." (PMID 35507134, 2022). "We favor the idea that in-depth biochemical and cellular analysis of patient derived BRCA2 variants with known clinical outcomes will help elucidate the features required for tumor suppressor functions." (PMID 36098506, 2022). "Using these conditions, we found that pyridostatin effectively and specifically inhibited growth of xenograft tumours established from BRCA2‐deficient DLD1 cells." (PMID 35107878, 2022). "Pathogenic mutations at the OB-folds abrogated the binding with telomere G4, indicating that the way BRCA2 associates with telomere is innate to its tumor suppressor activity." (PMID 35697743, 2022). "Tumors with BRCA1 and BRCA2 mutations have demonstrated increased susceptibility to PARP inhibitors given the tumor cells defects in chromosomal repair and error-free DNA double-stranded breaks." (PMID 36359225, 2022). "In accordance with this reduced or even a complete loss of BRCA2 protein expression was detected in 50% of the investigated EP tumours." (PMID 34045664, 2022).